SST (somatostatin)
Diseases named in the same sentence as SST in open-access papers (continued):
Sharing a sentence is not in itself a finding about the gene and the disease.
psychosis (4 papers, 2008 to 2026). "The genes down-regulated in psychosis include neuropeptide genes such as somatostatin (SST), neuropeptide Y (NPY) and tachykinin (TAC1)." (PMID 18992145, 2008). "Future GABA PET studies in early psychosis may address this hypothesis by examining PVALB interneuron-mediated inhibition with [11C]flumazenil and SST interneuron-associated inhibition with [11C]Ro15-4513, while carefully considering the effects of antipsychotic medication." (PMID 35440709, 2022). "Using a quantitative PCR, we validated a set of genes such as up-regulated metallothioneins (MT1E, MT1F, MT1H, MT1K, MT1X, MT2A and MT3) and down-regulated neuropeptides (SST, TAC1 and NPY) in the dorsolateral prefrontal cortex of psychosis patients." (PMID 18992145, 2008). "We have also confirmed that expression of the neuropeptide genes are down-regulated in psychosis; NPY (p = 0.02, FC -1.32), NR4A2 (p = 0.01, FC -1.39), SST (p = 0.001, FC -1.57) and TAC1 (p = 0.01, FC -1.6)." (PMID 18992145, 2008). "Taken together, these findings may suggest that SST interneuron dysfunction in the hippocampus and PVALB interneuron abnormalities in cortical and subcortical regions may play a role in the onset of psychosis." (PMID 35440709, 2022).
rheumatoid arthritis (4 papers, 2019 to 2024). A chronic, systemic autoimmune disorder characterized by inflammation in the synovial membranes and articular surfaces. "Consequently, there is growing interest in exploring the therapeutic potential of SST and its analogs for inflammatory diseases, such as inflammatory bowel diseases and rheumatoid arthritis, despite the mechanism underlying the regulatory effect of SST on T-cell remain largely unknown." (PMID 38426092, 2024). "As far as radiolabeled peptides are concerned, it is important to emphasize the increasing use of somatostatin (SST) analogues targeting somatostatin receptors (SSTR) in inflammatory diseases, particularly in rheumatoid arthritis (RA), Sjögren syndrome (SS), and autoimmune thyroid diseases." (PMID 31463594, 2019).
thyroid cancer (4 papers, 2014 to 2022). "Signaling through mTOR and somatostatin pathway is implicated in thyroid cancer development." (PMID 30807575, 2019). "Because a given receptor must display at least moderately strong expression intensity (i.e., IRS ≥6) to be clinically useful as a target structure, our results indicate that very few patients with thyroid cancer would likely benefit from SST- or CXCR4-based diagnostics or therapy." (PMID 35799158, 2022). "Moreover, in thyroid carcinoma cell lines, somatostatin is able to inhibit cell proliferation even in anaplastic thyroid carcinoma cell lines." (PMID 24465589, 2014). "Therefore, targeting of tumour microvessels using anti-SST or anti-CXCR4 therapies might represent a promising (additional) therapeutic strategy for thyroid carcinomas." (PMID 35799158, 2022). "The aim of the present study was to comprehensively re-evaluate SST and CXCR4 expression in a large set of thyroid carcinoma samples of all four entities by immunohistochemistry using well-characterised rabbit monoclonal antibodies." (PMID 35799158, 2022). "In contrast to the majority of the existing data for SSTs and CXCR4, our investigations revealed low levels of SST and CXCR4 expression in thyroid carcinoma samples overall." (PMID 35799158, 2022). "Pronounced intra-individual variability in SST and CXCR4 expression is well documented in the literature for many tumour entities and has also been noted for thyroid cancer." (PMID 35799158, 2022). "SST and CXCR4 expression levels are generally low in thyroid carcinomas." (PMID 35799158, 2022). "Whereas no major differences in SST expression were noted between the four thyroid carcinoma entities, CXCR4 expression was significantly higher in highly malignant APC than in well-differentiated PTC and FTC." (PMID 35799158, 2022). "SST- or CXCR4-based diagnostics or therapy in thyroid carcinomas should not be considered in general but may be feasible in single cases with high levels of expression of these receptors." (PMID 35799158, 2022). "Therefore, SST- or CXCR4-based diagnostics or therapy in thyroid carcinomas should not be considered in general, although they might be feasible in single cases with high expression of these receptors." (PMID 35799158, 2022).
viral infection (4 papers, 2021 to 2025). "While our model results in less viral infection near the cortical edge, the loss of PV and SST was not proportional to the density of mCherry + cells; SST cell density reductions were most prominent in the mid-to-deeper cortical layers." (PMID 41255962, 2025). "Before patch-clamp recording, we checked brain slices for td-Tomato fluorescence to confirm the presence of SST interneurons and for GFP to confirm viral infection." (PMID 40211051, 2025). "At 68–72 h post-viral infection, PRV labeled neurons were present only in the BRN, being preponderant in CRF+ neurons with few SST+ BRN neurons labeled from the bladder." (PMID 34675794, 2021). "Using dual viral infection to express the inhibitory Designer Receptors Exclusively Activated by Designer Drugs (DREADD), hM4D(Gi), selectively in SST-positive cells, we inhibited SST-expressing neurons by administering Clozapine N-oxide (CNO)." (PMID 36639888, 2023).
alcohol dependence (3 papers, 2021 to 2025). Physical and psychological dependence on alcohol. "Alcohol binge drinking disinhibited pyramidal neurons by augmenting SST neurons-mediated GABA release and synaptic strength onto other GABAergic populations and reducing spontaneous inhibitory transmission onto pyramidal neurons." (PMID 34112959, 2021). "Alcohol binge drinking augmented the inhibitory strength of SST neurons onto other non-SST neurons, thereby disinhibiting pyramidal neurons via decreased inhibitory transmission and increased intrinsic excitability." (PMID 34112959, 2021).
Arthritis (3 papers, 2014 to 2021). Inflammation of a joint. "We have also shown that sensory nerve-derived somatostatin is an important endogenous inhibitor in the adjuvant-induced arthritis model of the rat." (PMID 25524130, 2015). "Their activation inhibits the characteristic arthritis symptoms (edema, inflammatory cell activation and functions) at least partially through somatostatin release, but despite this potent anti-inflammatory role, they mediate the later pain response." (PMID 25524130, 2015). "Some studies showed that somatostatin stimulates the production of IL-1β, TNF-α, and/or IL-6 by human blood cells, as well as the expression of IL-1β in articular tissues of rats with ongoing adjuvant-induced arthritis." (PMID 25530957, 2014). "SST depletor (CSH) and non-selective SST receptor antagonist (C-SOM) abolished the inhibitory effect of curcumin on arthritis, this supported the hypothesis that SST from GI mediates the inflammation response." (PMID 33796080, 2021).
atherosclerosis (3 papers, 2017 to 2023). A disease characterized by the build-up of fatty material and calcium deposition in the arterial wall resulting in partial or complete occlusion of the arterial lumen. "Thus, LPL and BMP7, which are associated with insulin and glucose homeostasis, and MCP2 and SST, which are associated with regulation of immune system processes and cell migration, may play important roles in both the formation and regression of atherosclerosis." (PMID 30958112, 2019).
Atrophy (3 papers, 2013 to 2024). Any weakening or degeneration, especially through lack of use. "While this paradigm increases the dendritic complexity and the spine density of excitatory neurons, SST interneurons face a noticeable atrophy." (PMID 38622200, 2024). "We used immunolabeling to detect PARV+ interneurons in fixed sections, and corrected for disease-related striatal atrophy by expressing PARV+ interneuron counts in ratio to interneurons co-containing somatostatin and neuropeptide Y (whose numbers are unaffected in HD)." (PMID 24014043, 2013).
breast tumor (3 papers, 2006 to 2023). "SST and SSTRs have been studied for their antiproliferative effect in various types of tumours, including breast tumours." (PMID 38203605, 2023). "It is believed that there are direct and indirect mechanisms of action of SST on breast tumour cells." (PMID 38203605, 2023). "Despite SSTR and ErbB colocalization, low abundance of SSTRs alongside high expression of ErbBs within the same cell may account for the failure of SST treatment of breast tumor or other ErbB-expressing tumors." (PMID 16519802, 2006).
cognitive decline (3 papers, 2023 to 2025). "As an inhibitory neurotransmitter, the SST protein downregulation in inhibitory neurons may cause an excitatory-inhibitory imbalance, which may cause synaptic dysfunction and cognitive decline in AD." (PMID 41458885, 2025). "Pathogenesis of the disease was further associated with somatostatin (SST) inhibitory interneuron loss and preservation of intratelencephalic-projecting pyramidal cells was associated with a slower rate of cognitive decline in human postmortem AD samples." (PMID 36981041, 2023).
dyspepsia (3 papers, 2014 to 2023). An uncomfortable, often painful feeling in the stomach, resulting from impaired digestion. "The present findings of increased gastrin and decreased somatostatin in all IBS subtypes may cause a high level of gastric acid secretion, which may account for the high incidence of dyspepsia and gastro-oesophageal reflux observed in patients with IBS." (PMID 25110039, 2014). "The increase in gastrin cell density and the decrease in somatostatin cell density in all IBS subtypes may cause high levels of gastric secretion, which may in turn contribute to the high incidence of dyspepsia and gastro-oesophageal reflux observed in patients with IBS." (PMID 25110039, 2014). "An increase in gastrin and a decrease in somatostatin in all IBS subtypes may result in high levels of gastric acid secretion, which may explain the frequent occurrence of dyspepsia and gastroesophageal reflux in IBS patients." (PMID 37296188, 2023).
endometrial cancer (3 papers, 2020 to 2022). Primary or metastatic malignant neoplasm involving the endometrium (mucous membrane that lines the endometrial cavity). "In addition, the overexpression of LGR5 and SST in endometrial cancer reported with the Oncomine database was also confirmed with GEPIA." (PMID 35163161, 2022). "Urine samples of endometrial cancer patients (n = 42) and healthy controls (n = 46) were separated into three fractions (full void urine, urine sediment, and urine supernatant) and tested for three DNA methylation markers (GHSR, SST, ZIC1)." (PMID 33143739, 2020). "Moreover, it has also been reported that LGR5, SST, ZNF558, and PTGDS may be involved in the development and progression of endometrial cancer." (PMID 35163161, 2022).
epileptic seizures (3 papers, 2024 to 2026). "Initially, various types of GABAergic neurons, including parvalbumin (PV), somatostatin (SST), and vasoactive intestinal peptide (VIP) neurons, are employed in epileptic seizures, followed by glutamatergic neurons." (PMID 40217549, 2024).
gastroenteropancreatic neuroendocrine tumors (3 papers, 2015 to 2023). "Gastroenteropancreatic neuroendocrine tumors (GEP-NETs), although curable when localized, frequently metastasize and require management with systemic therapies, including somatostatin analogues, peptide receptor radiotherapy, small-molecule targeted therapies, and chemotherapy." (PMID 36551599, 2022).
head and neck squamous cell carcinoma (3 papers, 2015 to 2022). A squamous cell carcinoma that arises from any of the following anatomic sites: lip and oral cavity, nasal cavity, paranasal sinuses, pharynx, larynx, and salivary glands. "The aim of this study was to define somatostatin (SST) and somatostatin receptor type 1 (SSTR1) methylation profiles for head and neck squamous cell carcinoma (HNSCC) tumors at diagnosis and follow up and to evaluate their prognostic significance and value as a biomarker." (PMID 25734919, 2015).
Huntington disease (3 papers, 2011 to 2021). Huntington disease (HD) is a rare neurodegenerative disorder of the central nervous system characterized by unwanted choreatic movements, behavioral and psychiatric disturbances and dementia. "Our results indicate that SST and SSTRs might play an important role in regulation of neurodegeneration and targeting this pathway can provide a novel insight in understanding the pathophysiology of Huntington's disease." (PMID 21912697, 2011).
Hypercalcemia (3 papers, 2022 to 2026). An abnormally increased calcium concentration in the blood. "Despite initial tumour stabilisation following PRRT, she developed refractory hypercalcaemia, demonstrating only partial response to zoledronate, high-dose denosumab, and maximal somatostatin analogue therapy, and ultimately succumbed to progressive disease and metabolic deterioration." (PMID 41704230, 2026). "We suggest that endothelial SST expression mediates high radiopharmaceutical uptake by PAs and that SSA treatment can reduce hypercalcemia in PHPT patients." (PMID 39682626, 2024).
itch (3 papers, 2019 to 2024). "An additional observation in the somatostatin photostimulation study was the presence of itch related behaviors." (PMID 31713514, 2019). "Furthermore, our findings show that pharmacological impairment of the inhibitory tone by applying the peptide somatostatin was effective in inducing activation in a part of this itch-related population." (PMID 31719558, 2019). "The peptide somatostatin was thus able to activate a sub-population of Grpr-Cre.GCaMP6 neurons, results that complements the electrophysiological data and shows that the itch-related Grpr-Cre population is under inhibitory control that is released upon disinhibition induced by somatostatin." (PMID 31719558, 2019).
leukemia (3 papers, 2011 to 2016). A malignant (clonal) hematologic disorder, involving hematopoietic stem cells and characterized by the presence of primitive or atypical myeloid or lymphoid cells in the bone marrow and the blood. "Remaining candidates (N = 62) comprised BDNF-related genes (SST), MAPK-pathway genes (KRAS, IGF1R, GNG11 and RAP1A), genes related with leukemia (SFRP1) and Rho-Proteins (DHCR7 and RAB21)." (PMID 21569303, 2011).
melanoma (3 papers, 2003 to 2021). A malignant, usually aggressive tumor composed of atypical, neoplastic melanocytes. "In addition, the in vitro antiangiogenic effects of somatostatin and its analogues have been previously shown by studies on melanoma cells, which expressed one or more SSTR and were treated by using somatostatin or SSAs." (PMID 23119007, 2012). "A novel somatostatin analogue, TT-232 (which inhibits the proliferation of various cell cultures and transplantable mouse tumours), was examined regarding its effect on human melanoma and lymphoma xenografts as a single treatment or in combination with DTIC (dacarbazine) and etoposide." (PMID 12556972, 2003). "However, in melanoma therapy, somatostatin analogs did not significantly inhibit melanoma evolution." (PMID 34068618, 2021).
neuropathic pain (3 papers, 2023 to 2025). Chronic pain caused by damage to nerve fibers. "In this model, neuropathic pain is associated with increased spontaneous activity of layer V pyramidal neurons (LV-PNs) in the S1, partly attributed to the reduced activity of somatostatin-expressing inhibitory neurons (SST+ INs), which normally suppress LV-PNs." (PMID 40228867, 2025). "We investigated the effects of voluntary running (VR) on FosB+ cells and GABAergic interneurons (parvalbumin-positive [PV+] and somatostatin-positive [SOM+]) in the vHPC-CA1 in neuropathic pain (NPP) model mice." (PMID 36788313, 2023). "In terms of inputs, it is necessary to determine whether such pain-related brain areas directly project to SST interneurons in the mPFC and how they change in the context of neuropathic pain." (PMID 40211051, 2025).
ovarian carcinoma (3 papers, 2023 to 2024). A malignant neoplasm originating from the surface ovarian epithelium. "The use of SST analogs as a potential therapeutic approach in ovarian cancer treatment is further supported by recent studies describing the inhibition of cell proliferation and apoptosis induction." (PMID 38203605, 2023).
rectal cancer (3 papers, 2016 to 2021). A primary or metastatic malignant neoplasm that affects the rectum. "Interestingly, the results showed that SST was significantly downregulated in the gastrointestinal tract malignancies of esophageal, stomach, colon, and rectal cancers." (PMID 32243066, 2020). "Ten of the 36 (EYA4, FOXI2, CNRIP1, SFRP1, ADHFE1, C2orf40, MAL, PHACTR3, SST, TMEFF2) were known as rectal cancer related genes with aberrant methylation." (PMID 27566576, 2016). "In addition, three hub genes, including SST, SSTR2, and CXCL12, were significantly downregulated in the rectal cancer tissues." (PMID 34269159, 2021). "Besides CXCL1, CXCL2, and CXCL3, we mined seven other hub genes related to rectal cancer, including SAA1, AGT, GNG4, SST, SSTR2, GAL, and CXCL12." (PMID 34269159, 2021).
thyroid neoplasm (3 papers, 2009 to 2023). "Although controversies exist, the role of SST and its analogues in thyroid tumour diagnosis and prognosis cannot be denied in a receptor and tumour-specific manner." (PMID 38203605, 2023). "SST works via binding to five different receptors and exerts antiproliferative effect and induced apoptosis that account for potential therapeutic approaches in cancer treatment, including thyroid tumours." (PMID 38203605, 2023). "It suggests that somatostatin multiligand analogs or selective SSTR 1 agonists may represent a further useful approach for the thyroid tumors treatment." (PMID 19173713, 2009). "It suggests that somatostatin multiligand analogs or selective SSTR 1 agonists may be used in thyroid tumors treatment." (PMID 19173713, 2009). "Several previous studies have shown the use of radiolabeled SST analogs in treating differentiated and nondifferentiated thyroid tumours." (PMID 38203605, 2023).
ulcer (3 papers, 2017 to 2025). "CCK contributes to mucosal defense by stimulating somatostatin release, enhancing blood flow (hyperemia), and promoting sensory nerve activation at ulcer sites." (PMID 40708688, 2025). "Regulates pain, cognition, and feeding behavior; accelerates ulcer healing via somatostatin release and hyperemia." (PMID 40708688, 2025). "However, the depletion of somatostatin might be the main factor sustaining the development of cysteamine-induced ulcers, and treatment with somatostatin prevents Cys-induced ulcers formation and has an inhibitory effect on ghrelin secretion." (PMID 28448444, 2017). "Results showed that acute systemic administration of H3R agonist (R)-α-methylhistamine (RAMH, 100 mg/kg, i.g.)significantly reduced the severity of ulcer index, increased gastric acid output, and increased mucosal PGE2 production without any alteration of somatostatin concentration in gastric juice." (PMID 31572174, 2019).
AL amyloidosis (2 papers, 2019 to 2023). AL Amyloidosis is a plasma cell disorder characterized by the aggregation and deposition of insoluble amyloid fibrils derived from misfolding of monoclonal immunoglobulin light chains usually produced by a plasma cell tumor. "In conclusion, the novel biomarkers sST 2 and GDF-15 showed satisfactory prognostic values for overall survival in patients with AL amyloidosis." (PMID 31434944, 2019).
alcohol use disorder (2 papers, 2020 to 2021). "Future studies may merit from examination of the modulatory action of SST peptide, in healthy states and alcohol abuse-associated conditions." (PMID 32536856, 2020). "Somatostatin (SST) neurons, a subtype of GABAergic neurons found throughout the brain, are a novel neural target with potential treatment implications in affective disorders, yet their role in alcohol use disorders (AUD) remains to be explored." (PMID 32536856, 2020).